LNC-LBCS (lncRNA bladder and prostate cancer suppressor, hnRNPK interacting)
Synonyms: LBCS
Gene: Long non-coding RNA gene on chromosome 6 (19,306,534 to 19,839,080, reverse strand). Ensembl gene ENSG00000228412.
Diseases named in the same sentence as LNC-LBCS in open-access papers:
LNC-LBCS is named in the same sentence as 4 diseases in open-access papers, as found by Europe PMC text mining. Sharing a sentence is not in itself a finding about the gene and the disease. The quoted sentences say what the papers report.
bladder cancer (7 papers, 2019 to 2025). "Lnc-LBCS serves a tumor-suppressive effect in bladder cancer stem cells, which is tightly related to prognosis, treatment response, and clinical stage." (PMID 37183262, 2023). "For instance, lnc-LBCS could dramatically attenuate bladder cancer initiation and chemo-resistance via guiding hnRNPK-EZH2 complex to the SOX2 promoter and mediating histone H3 lysine 27 trimethylation (H3K27me3)." (PMID 31335317, 2019). "lnc-LBCS repress the SRY-box 2 (SOX2) transcription, which is essential factor in the self-renewal of bladder cancer stem cell populations." (PMID 40149464, 2025).
prostate carcinoma (1 paper, 2019). A carcinoma that arises from epithelial cells of the prostate gland. "Lnc-LBCS functions as a novel AR translational regulator that suppresses castration resistance of prostate cancer by interacting with hnRNPK." (PMID 31221168, 2019).
LNC-LBCS also shares sentences with these, for which no sentence is quoted: tumor (3 papers); cancer (1).